INF2 (inverted formin 2)
Diseases named in the same sentence as INF2 in open-access papers (continued):
Sharing a sentence is not in itself a finding about the gene and the disease.
glioblastoma (3 papers, 2020 to 2024). The most malignant astrocytic tumor (WHO grade IV). "Furthermore, moderate/high expression of INF2 in glioblastoma tissue was associated with worse outcome." (PMID 32727404, 2020). "Moderate/high expression of INF2 in glioblastoma tissue is associated with worse outcome." (PMID 32727404, 2020). "Three proteins have been identified as upregulated in recurrent glioblastoma and highly heterogeneous across patients: brain enriched myelin associated protein 1 (BCAS1), inverted formin 2 (INF2), and F-Box Protein 2 (FBXO2)." (PMID 39513861, 2024). "Using immunohistochemistry, we discovered that formins FHOD1 and INF2 are frequently expressed in glioblastoma tissue." (PMID 32727404, 2020). "The glioblastoma study also showed that the elevated level of Ca2+ induced by SOCE led to actin cytoskeleton remodelling mediated by INF2." (PMID 32846966, 2020). "Using immunohistochemistry, we demonstrated expression of formin proteins FHOD1 and INF2 in glioblastoma tissues." (PMID 32727404, 2020). "FBXO2-positive glioma cells were mostly associated with regions of the tumor with high immune reactivity and neurodevelopmental reactivation of the transcription program, while BCAS1 and INF2 were less specific and more widely diffused across the different regions of the glioblastoma." (PMID 39513861, 2024). "When specific inhibiting compounds become available, INF2 could be a target in the search for novel glioblastoma therapies." (PMID 32727404, 2020). "Formins FHOD1 and INF2 participate in glioblastoma cell migration." (PMID 32727404, 2020). "Taken together, our in vitro and tissue studies suggest a pivotal role for INF2 in glioblastoma." (PMID 32727404, 2020). "For INF2, 18 glioblastomas showed high expression, 72 low expression, and 3 specimens were missing." (PMID 32727404, 2020). "To evaluate whether FHOD1 or INF2 expression is altered in areas of diffuse infiltration as compared to solid tumour areas, we studied 10 representative glioblastoma samples as whole slides." (PMID 32727404, 2020). "To establish whether the most interesting formins from the transcriptomics analysis, FHOD1 and INF2, are expressed as protein in human glioblastoma, we performed immunohistochemistry on human glioblastoma samples." (PMID 32727404, 2020). "Therefore, the moderate/high expression of FHOD1 and INF2 in a subset of glioblastomas can be considered as overexpression." (PMID 32727404, 2020). "In these samples, five glioblastomas were found to have diffusely infiltrating cells expressing moderate/high FHOD1 and/or INF2 in more than 20% of tumour cells, while the solid tumour showed absent/low expression." (PMID 32727404, 2020). "Using immunohistochemistry, we studied the expression of two formins, FHOD1 and INF2, in tissue samples from 93 IDH-wildtype glioblastomas." (PMID 32727404, 2020). "Previous studies that have focused on other formins than INF2 and FHOD1 have also indicated that individual formins participate in glioblastoma cell migration/invasion." (PMID 32727404, 2020). "In 93 samples of IDH-wildtype glioblastomas, FHOD1 and INF2 expression (scores 1–3) could be detected in 84 and 46% of cases, respectively." (PMID 32727404, 2020). "Using a knockdown approach, we could for the first time show that the expression of INF2 and FHOD1 is necessary for efficient migration of glioblastoma cells." (PMID 32727404, 2020).
glomerulosclerosis (3 papers, 2014 to 2025). A hardening of the kidney glomerulus caused by scarring of the blood vessels. "The INF2 morphants showed markedly increased edema and glomerulosclerosis." (PMID 26086034, 2014). "In support of this hypothesis, we have demonstrated that a proteasome inhibitor (PI), bortezomib, could attenuate podocyte injury and prevent glomerulosclerosis in a mouse model of INF2-R218Q-mediated FSGS, by preventing the UPS-mediated depletion of SD proteins." (PMID 39621430, 2025).
cardiomyopathy (2 papers, 2021 to 2024). A disease of the heart muscle or myocardium proper. "Conclusively, our research elucidates the intricate interplay between DNA-PKcs and INF2 in the modulation of mitochondrial function and dynamics during sepsis-induced cardiomyopathy." (PMID 38464839, 2024).
glioma (2 papers, 2024). A benign or malignant brain and spinal cord tumor that arises from glial cells (astrocytes, oligodendrocytes, ependymal cells). "INF2 shows strong positivity (>75%) in liver cancer, head and neck cancer, and glioma." (PMID 39329952, 2024).
placental insufficiency (2 papers, 2018 to 2021). Failure of the placenta to deliver an adequate supply of nutrients and oxygen to the fetus. "Furthermore, global loss of Inf2 in mice recapitulates maternal and fetal phenotypes of placental insufficiency." (PMID 29309034, 2018). "Inf2-deficient mice demonstrated impaired spiral artery remodeling, hypertension, fetal growth restriction, and altered placental development, identifying the Inf2 null mouse as a novel model of placental insufficiency." (PMID 29309034, 2018). "Both maternal and fetal phenotypes of placental insufficiency were observed in the Inf2-lacking mice, highlighting the essential roles of Inf2 during pregnancy." (PMID 33477586, 2021).
actinopathy (1 paper, 2023). "Histologic analysis of biopsied sural nerves from patients with CMT/FSGS associated with INF2 mutations revealed that non-myelinating cells produce filopodia-like supernumerary protrusions with abnormal actin accumulation in the cytoplasm, suggesting the presence of global actinopathy." (PMID 37491439, 2023).
Adult onset (1 paper, 2024). Onset of disease manifestations in adulthood, defined here as at the age of 16 years or later. "The commonest genes affected in adult-onset FSGS (COL4A3–COL4A5,GLA ) have ocular abnormalities but not the other frequently affected genes (ACTN4, CD2AP, INF2, TRPC6)." (PMID 37578539, 2024).
Atrophy (1 paper, 2025). Any weakening or degeneration, especially through lack of use. "We observed the typical physical manifestations of INF2-related CMT for our patients including atrophy of the forearm and intrinsic hand muscles (so-called “claw-hand”)." (PMID 39857711, 2025).
autosomal dominant tubulointerstitial kidney disease (1 paper, 2025). "These included 3 cases of autosomal dominant tubulointerstitial kidney disease (UMOD), 3 cases of hereditary FSGS/steroid resistant nephrotic syndrome (INF2 × 2, WT1 × 1), 3 cases of nail-patella-like renal disease (LMX1B), and 2 cases of MYH9-related disease." (PMID 40753325, 2025).
axonal neuropathy (1 paper, 2023). Any nerve disorder affecting the axon of a nerve. "In a manner similar to INF2, MFN2, encoding a mitochondria outer-membrane protein enriched at ER-mitochondria contact sites, causes an axonal neuropathy (CMT2A2) associated with disruption of ER-mitochondria interactions and mitochondrial trafficking." (PMID 37491439, 2023).
Cerebral ischemia (1 paper, 2019). Restriction of arterial blood supply to the brain associated with insufficient oxygenation to support the metabolic requirements of the tissue. "Similar to our findings, a recent study on a mouse model of cerebral ischemia/reperfusion also reported that Nurr1 upregulation was involved in the pathogenesis of cerebral reperfusion injury through activation of INF2-mediated mitochondrial fission." (PMID 33817160, 2019).
Cough (1 paper, 2022). A sudden, audible expulsion of air from the lungs through a partially closed glottis, preceded by inhalation. "We, therefore, inoculated one cat (INF1) by spraying it with the virus (sneeze/cough infection model) and another cat (INF2) by distributing the virus over its hair (licking infection model)." (PMID 35243589, 2022).
hereditary spastic paraplegia (1 paper, 2017). Hereditary spastic paraplegias (HSP) comprise a genetically and clinically heterogeneous group of neurodegenerative disorders characterized by progressive spasticity and hyperreflexia of the lower limbs. "Of note, there are nine genes among these targets that when mutated are known causes for inherited peripheral neuropathies (IPN) and hereditary spastic paraplegia (HSP) (Inf2, Sox10, Wnk1, Med25, Fa2h, Bscl2, Slc12a6, Kif1a and Kif5a)." (PMID 28077174, 2017).
homocystinuria (1 paper, 2020). An autosomal recessive inherited metabolic disorder caused by mutations in the CBS, MTHFR, MTR, and MTRR genes. "Recently, it has been identified that mutation in non-complement genes such as diacylglycerol kinase epsilon (DGKE), thrombomodulin (THBD), inverted formin 2 (INF2) and methylmalonic aciduria and homocystinuria cobalamin C (cbLC) type (MMACHC) can also trigger aHUS." (PMID 32838746, 2020).
Hyperglycemia (1 paper, 2024). An increased concentration of glucose in the blood. "This corroborates the synchronized upregulation of hyperglycemia-responsive dynein subunits that are colocalizes with inverted formin 2, a dynein regulating protein that is highly selectively expressed in podocyte cytosol." (PMID 38467599, 2024).
Hypertension (1 paper, 2018). The presence of chronic increased pressure in the systemic arterial system. "Loss of Inf2 alters maternal spiral artery remodeling, resulting in systemic hypertension late in pregnancy." (PMID 29309034, 2018).
Intellectual disability (1 paper, 2021). "Mutations of DIAPH1, FMN2, and INF2 are associated, to varying degrees, with intellectual disability and neurodevelopmental disorders." (PMID 34685534, 2021). "In the case of INF2, some patients with FSGS and associated CMT, probably with severe mutations or an unfavorable genetic background, present intellectual disability and central nervous system anomalies." (PMID 34685534, 2021).
ischemic stroke (1 paper, 2022). A stroke disorder caused by obstruction of blood flow to the brain, due to thrombotic (local blood clot formation) or embolic (due to a blood clot or other material traveling from another site) event. "We next asked whether INF2-driven actinification plays a role in neuronal survival following ischemic stroke." (PMID 36229429, 2022).
minimal change disease (1 paper, 2018). "Mutational analysis of INF2 was performed on 109 patients (mean age at onset 41.44 ± 18.91 years) with FSGS or minimal change disease (MCD); and also in 6 patients without renal biopsy who had already developed chronic kidney disease (CKD)/ESRD at the time of diagnosis." (PMID 30126379, 2018).
myocardial ischemia (1 paper, 2024). A disorder of cardiac function caused by insufficient blood flow to the muscle tissue of the heart. "INF2 is a novel mitochondrial dynamic regulator that is associated with activating mitochondrial fission and myocardial ischemia–reperfusion injury." (PMID 39329952, 2024).
neurofibromatosis (1 paper, 2025). A hereditary neoplastic syndrome in which tumors grow in the nervous system. "Our data suggest that the germline and/or somatic variants in schwannomatosis and/or neurofibromatosis genes may enhance the pathogenic effects of INF2 variants." (PMID 39857711, 2025).
oral cancer (1 paper, 2025). "In our study, we found INF2 to be overexpressed in both oral leukoplakia and oral cancer." (PMID 40818124, 2025).
osteosarcoma (1 paper, 2023). A usually aggressive malignant bone-forming mesenchymal neoplasm, predominantly affecting adolescents and young adults. "The diminished actin cable/bundles in HeLa cells expressing INF2 variants is consistent with some prior studies, but conflict with other studies that showed increased actin filaments at the ER and/or cytoplasm of osteosarcoma-derived U2OS cells." (PMID 37491439, 2023).
polyneuropathy (1 paper, 2016). A disease or disorder affecting more than one nerve. "In one of the two patients with histologically proven FSGS and a polyneuropathy, we identified a pathogenic mutation in the INF2 gene (patient 47)." (PMID 27088055, 2016).
renal dysfunction (1 paper, 2026). "Urinalysis and renal function tests are essential for the diagnostic workup, and if persistent proteinuria or renal dysfunction is detected, genetic testing for INF2 should be performed." (PMID 40985697, 2026). "Thus, urinalysis and renal function tests should be considered in pediatric patients suspected of CIDP, with the presence of proteinuria or renal dysfunction prompting genetic testing for INF2 variants." (PMID 40985697, 2026). "In our cohort, all patients with INF2 variants developed renal dysfunction, and none presented with isolated CMT." (PMID 40985697, 2026). "In conclusion, although INF2‐related CMT is relatively rare in Japan, it should be considered in pediatric patients with demyelinating neuropathy and early‐onset renal dysfunction, particularly if CIDP is suspected." (PMID 40985697, 2026).
schwannoma (1 paper, 2025). A benign, usually encapsulated slow growing tumor composed of Schwann cells. "Schwannoma could co-occur in patients with INF2-related CMT, particularly in whom the germline schwannomatosis-predisposing variants such as LZTR1 simultaneously exist." (PMID 39857711, 2025).
schwannomatosis (1 paper, 2025). The least frequent form of the rare genetic disorder neurofibromatosis. "Whole-exome sequencing with the genomic DNA from peripheral blood leukocytes showed that patient 1 with INF2 p.Gly73Asp had no germline, schwannomatosis-related gene variants including 22q loss of heterozygosity (LOH), NF1, NF2, LZTR1, SMARCB1, and COQ6." (PMID 39857711, 2025).
Thrombocytopenia (1 paper, 2021). A reduction in the number of circulating thrombocytes. "Two mutations in the DID of INF2 cause thrombocytopenia in the context of familial AHUS with (p.Val102Asp) or without (p.Arg177His) associated CMT." (PMID 34685534, 2021).
viral infection (1 paper, 2021). "Since both the mitochondria and ER were altered significantly in EV71 infected cells, we hypothesized that viral infection would affect INF2 expression." (PMID 34046026, 2021).
cancer (16 papers, 2013 to 2025). A tumor composed of atypical neoplastic, often pleomorphic cells that invade other tissues. "Intriguingly, cancer-associated INF2 mutants are stabilized because of impaired FBXO7-INF2 interaction and FBXO7-mediated INF2 polyubiquitination and degradation." (PMID 37344480, 2023). "Additionally, INF2 dysregulation is implicated in tumor progression and metastasis, with elevated expression observed in cancers such as glioblastoma, triple-negative breast cancer, and gastric cancer." (PMID 38233384, 2024). "This modification enhances HIPK2’s ability to phosphorylate HP1γ, promoting DNA repair, and inhibits INF2-mediated mitochondrial fission, thereby reducing the proliferation and invasion of cancer cells." (PMID 40391156, 2025). "The identification of ACTB, ACTN4, INF2, and MYL6 as DEDRGs that are implicated in both PD and various cancer types opens up exciting possibilities for developing novel therapeutic strategies for human patients." (PMID 39329952, 2024). "We found that INF2 mRNA expression was significantly upregulated in various cancer types, including EC when compared to corresponding normal tissues." (PMID 38233384, 2024). "To investigate potential alterations in INF2 expression levels in human cancers, we analyzed the publicly available TCGA dataset to evaluate the mRNA expression pattern of INF2 in human cancer specimens." (PMID 38233384, 2024). "Key genes (ACTIN1, LIMK1, CORO1C, INF2, SH3D21, CFL1, FSCN1, MYO1B) implicated in actin cytoskeleton organization were identified, suggesting their role in oral potentially malignant disorders and cancer progression." (PMID 40818124, 2025). "Furthermore, we showed that DDX17 can regulate the expression or AS of some cancer-related genes and speculated that INF2 may be a target gene of DDX17 in regulating AS in LUAD." (PMID 36164607, 2022). "INF2 may induce apoptosis or act as an oncogene in different cancers." (PMID 36164607, 2022). "In conclusion, our study highlights the potential of ACTB, ACTN4, INF2, and MYL6 as therapeutic targets and biomarkers for PD and cancer." (PMID 39329952, 2024). "In pan-cancer, the high expression of ACTB, ACTN4, and MYL6 in GBMLGG, LGG, MESO, and LAML had a poor prognosis, and the high expression of INF2 in LIHC, LUAD, UVM, HNSC, GBM, LAML, and KIPAN had a poor prognosis." (PMID 39329952, 2024). "Investigating the resistance mechanisms of nontransformed cells could provide insight into the role of INF2 in specific cancers and help explain the differential susceptibility of podocytes, Schwann cells, and sensory neurons, especially if the observed axonal loss is a direct effect." (PMID 39586895, 2024). "DSTN and FLNB were downregulated when ACTIN4, INF2, MHY10, FLNA, PDLIM1, and IQGAP1 were upregulated in THCA cancer tissues." (PMID 38584831, 2024). "MHY9, INF2, FLNA, MYH10, FLNB, FLN1, and ACTB were upregulated in HNSC cancer tissues." (PMID 38584831, 2024). "This study found that ACTB, ACTN4, INF2, and MYL6 are closely related to PD and pan-cancer and can be used as candidate genes for the diagnosis, prognosis, and therapeutic biomarkers of neurodegenerative diseases and cancers." (PMID 39329952, 2024). "Considering the oncogenic functions of INF2 in cancers, we infer that FBXO7 may inhibit ECa cell proliferation and migration partly in an INF2-dependent manner." (PMID 37344480, 2023).
tumor (14 papers, 2020 to 2025). "Analysis of the TCGA EC dataset revealed that INF2 mRNA expression levels were positively correlated with tumor stages." (PMID 38233384, 2024). "Our results showed a substantial upregulation of INF2 protein in EC tissues compared to adjacent normal tissues, and that INF2 expression increased with FIGO tumor stage (IA to III)." (PMID 38233384, 2024). "Taken together, the analysis of the TCGA cohort and our sample cohort consistently suggest that INF2 expression is aberrantly increased in EC, and is correlated with advanced tumor stage and prognosis in EC patients." (PMID 38233384, 2024). "INF2 has a poor prognosis with high expression in seven tumor types (LIHC, LUAD, UVM, HNSC, GBM, LAML, KIPAN)." (PMID 39329952, 2024). "By contrast, Yap1KD; Gp130FF tumor organoids showed more prominent expression of Chit1 (marker for adaptive immune responses), Cidea (apoptosis), and Inf2 (cell adhesion)." (PMID 37957015, 2024). "Results showed that ACTB, DSTN, FLNA, IQGAP1, MYL6, and TLN1 were overexpressed in normal tissues, while CD2AP and INF2 were overexpressed in tumor tissues." (PMID 37325625, 2023). "Additionally, subcutaneous inoculation of parental and INF2 KO HEC-1B cells in nude mice showed that INF2 KO significantly attenuated HEC-1B xenograft tumor growth." (PMID 38233384, 2024). "We found that INF2 is significantly overexpressed in tumor tissues." (PMID 37344480, 2023). "For instance, phosphorylation of INF2 by AMPK reportedly promotes mitochondrial fission and enhanced tumor cell adaptation to energy stress, thereby facilitating tumor progression in certain settings." (PMID 40806980, 2025). "Additionally, a study indicated that the elimination of INF2 could reduce tumor cell proliferation." (PMID 40818124, 2025). "In addition to its degradative functions, SPOP also performs tumor-suppressive roles by regulating the non-degradative ubiquitination of certain substrates, such as inverted formin 2 (INF2) and myeloid differentiation primary response protein 88 (MyD88)." (PMID 40483310, 2025).